MCOLN1 (mucolipin TRP cation channel 1)
Diseases named in the same sentence as MCOLN1 in open-access papers (continued):
Sharing a sentence is not in itself a finding about the gene and the disease.
melanoma (18 papers, 2019 to 2025). A malignant, usually aggressive tumor composed of atypical, neoplastic melanocytes. "In melanoma, it is reported that Ca2+ channel mucolipin 1 (MCOLN1) is preferentially required for the survival and proliferation of melanoma cells by negatively regulating MAPK and mTORC1 signaling." (PMID 35563798, 2022). "Additionally, deficiency of MCOLN1 and TRPML1 hinders the growth of patient-derived melanoma cells through the interruption of macropinocytosis and depletion of serine in both in vitro and in vivo experiments." (PMID 38247807, 2024). "Additionally, macropinocytosis is upregulated in melanoma cells relative to normal melanocytes and is sustained by MCOLN1." (PMID 35563798, 2022).
glioma (11 papers, 2019 to 2023). A benign or malignant brain and spinal cord tumor that arises from glial cells (astrocytes, oligodendrocytes, ependymal cells). "The results revealed that all hub genes were amplified, deleted, and mutated in glioma, among which MCOLN1 displayed the highest incidence rate (1.8%)." (PMID 35625048, 2022). "We revealed that all of the hub genes were amplified, deleted, and mutated in glioma, with MCOLN1 exhibiting the highest incidence rate (1.6%)." (PMID 35625048, 2022). "In our present study, the results showed that the expression of TRPC1 and TRPC3 was significantly increased in glioma with IDH mutation status and 1p/19q codeletion status, while the expression of TRPC6, MCOLN1, MCOLN2, and MCOLN3 was significantly decreased." (PMID 35625048, 2022). "Higher levels of TRPC4, TRPC6, MCOLN1, MCOLN2, and MCOLN3 were significantly associated with shorter OS times in glioma." (PMID 35625048, 2022). "Among the eight final identified hub genes, higher expression levels of TRPC1, TRPC3, and TRPC5 were significantly associated with longer OS time in glioma, while higher expression levels of TRPC4, TRPC6, MCOLN1, MCOLN2, MCOLN3 were significantly associated with shorter OS time." (PMID 35625048, 2022). "The gene expression levels of TRPC1, TRPC3, and TRPC5 were significantly higher in low-grade glioma (LGG), while the levels of TRPC4, TRPC6, TRPM7, MCOLN1, MCOLN2, and MCOLN3 were significantly higher in high-grade glioma (HGG)." (PMID 35625048, 2022).
Parkinson disease (11 papers, 2016 to 2025). A progressive degenerative disorder of the central nervous system characterized by loss of dopamine producing neurons in the substantia nigra and the presence of Lewy bodies in the substantia nigra and locus coeruleus. "The changes observed in Mcoln1−/− microglia showed significant overlap with alterations previously reported for other common neuroinflammatory disorders including Alzheimer’s, Parkinson’s, and Huntington’s diseases." (PMID 31883529, 2019).
mucolipidosis (6 papers, 2016 to 2022). A group of inherited lysosomal storage diseases characterized by accumulation of lipids and carbohydrates in the tissues, resulting in mental disabilities and skeletal malformations. "This typically doubles the number of detected aberrant events and identified a pathogenic intron retention in MCOLN1 causing mucolipidosis." (PMID 33483494, 2021). "Mutations in MCOLN1 are associated with mucolipidosis (OMIM #605248)." (PMID 28604674, 2017).
non-small cell lung carcinoma (5 papers, 2019 to 2025). A group of at least three distinct histological types of lung cancer, including non-small cell squamous cell carcinoma, adenocarcinoma, and large cell carcinoma. "Downregulated MCOLN1 has been associated with decreased lysosome-autophagy activity and suppressed tumor progression in non-small cell lung cancer (NSCLC)." (PMID 38188686, 2023).
iron deficiency (3 papers, 2015 to 2023). "Total iron content in unperfused brain is not significantly different between Mcoln1−/− and wild-type littermate mice, suggesting that the observed maturation delay or loss of oligodendrocytes might be caused by impaired iron handling, rather than by global iron deficiency." (PMID 26398942, 2015).
Anxiety (2 papers, 2023 to 2024). Intense feelings of nervousness, tension, or panic often arise in response to interpersonal stresses. "Collectively, literature mining analysis suggests that long-term CR biomarker, C1QA, and regulatory gene MCOLN1 may play important roles in several health conditions, including anxiety, depression, stress, and neurodegenerative diseases as well as aging itself." (PMID 38094940, 2023).
colon cancer (2 papers, 2023). "MCOLN1, a member of the mucolipin family of transient receptor potential channels (TRPMLs), is significantly differentially expressed among colon cancer cells." (PMID 37072452, 2023). "The signature we constructed consists of three genes (MCOLN1, TRPM5, and TRPV4), all identified as independent prognostic and risk factors for colon cancer through the multivariate Cox regression model." (PMID 38188686, 2023). "In this study, we found that MCOLN1 is a novel target of TSA for the treatment of colon cancer." (PMID 37072452, 2023). "Forever, further studies are required to identify the biological processes of MCOLN1 and TSA in colon cancer." (PMID 37072452, 2023).
colorectal cancer (2 papers, 2023 to 2025). A primary or metastatic malignant neoplasm that affects the colon or rectum. "MCOLN1 and TUBA1A were associated with both TSA- and colorectal cancer cell line-specific effects." (PMID 37072452, 2023).
gastric cancer (2 papers, 2022 to 2025). A primary or metastatic malignant neoplasm involving the stomach. "In summary, our findings reveal that PITX2 is significantly linked to unfavorable outcomes in gastric cancer and modulates the expression of lysosomal exocytic genes, including MCOLN1 and RAB3A, which enhance the secretion of LGALS1 and IGFBP7." (PMID 40995693, 2025). "In current investigation, we identify paired like homeodomain 2 (PITX2) as an essential transcriptional coordinator of lysosomal exocytosis genes MCOLN1 and RAS‐related protein Rab‐3A (RAB3A), which is linked to an adverse outcome in gastric cancer." (PMID 40995693, 2025). "Furthermore, oncogenic autophagy in gastric cancer cells were demonstrated to be controlled by mucolipin TRP cation channel 1 (MCOLN1), a lysosomal cation channel, via the mediation of zinc influx into the cytosol." (PMID 36091106, 2022). "Mining the Kaplan‐Meier Plotter database revealed that up‐regulation of MCOLN1 (P = 4.6 × 10−2 and 4.4 × 10−2), RAB3A (P = 7.4 × 10−7 and 5.5 × 10−6), or LAMP1 (P = 3.2 × 10−3 and 2.3 × 10−2) was associated with poor overall or event‐free survival in gastric cancer patients." (PMID 40995693, 2025). "In this study, we found that 1‐83 amino acids of HOXA1 was able to interact with N‐terminal transactivation domain of PITX2, resulting in enhanced PITX2 activity to drive transcription of MCOLN1 and RAB3A in gastric cancer cells." (PMID 40995693, 2025). "Clinically, elevated expression of HOXA1, PITX2, MCOLN1, RAB3A, LGALS1, and IGFBP7 constitutes a prognostic signature correlating with poor outcomes of gastric cancer patients." (PMID 40995693, 2025). "Compared to their para‐tumoral tissues, higher levels of HOXA1, PITX2, MCOLN1, and RAB3A were observed in gastric cancer specimens." (PMID 40995693, 2025). "Mechanistically, HOXA1‐PITX2 complex facilitates the expression of mucolipin 1 (MCOLN1) and RAS‐related protein Rab‐3A (RAB3A), which drive lysosomal exocytosis of galectin‐1 (LGALS1) and insulin like growth factor binding protein 7 (IGFBP7) from senescent gastric cancer cells." (PMID 40995693, 2025). "Since MCOLN1 and RAB3A contribute to Ca2+ release and trafficking essential for lysosomal exocytosis, we further determined whether PITX2 could impact the biological characteristics of senescent gastric cancer cells." (PMID 40995693, 2025).
lymphedema (2 papers, 2024 to 2025). Excess fluid collection in tissues, causing swelling. "In the present study, we analyzed data from the GEO database and found that lymphedema is closely related to the Mcoln1 gene and we successfully constructed a mouse model of lymphedema by disrupting the lymphatic vessels in the tail, revealing milder edema symptoms in TRPML1-knockout mice." (PMID 39637010, 2024).
muscular dystrophy (2 papers, 2017 to 2025). Muscular dystrophy (MD) refers to a group of more than 30 genetic diseases characterized by progressive weakness and degeneration of the skeletal muscles that control movement. "One encoded an intracellular Ca2+ channel protein (Mcoln1), which was required for sarcolemma repair to prevent muscular dystrophy." (PMID 29312436, 2017).
Pancreatic cancer (2 papers, 2022 to 2024). "Pancreatic cancer cells harboring oncogenic RAS mutations exhibit an elevated level of MCOLN1, encoding the lysosomal calcium channel TRPML1." (PMID 38672219, 2024). "The prediction model based on MCOLN1, PKD1, TRPC3, and TPRC7 can also predict the prognosis of pancreatic cancer." (PMID 35898870, 2022).
prostate carcinoma (2 papers, 2022 to 2025). A carcinoma that arises from epithelial cells of the prostate gland. "TRPML1, encoded by gene MCOLN1, and TRPML2, encoded by gene MCOLN2, were expressed at moderate to high levels in 80% and 90% of the prostate cancer samples examined." (PMID 40332161, 2025).
bipolar disorder (1 paper, 2024). A disorder of the brain that causes unusual shifts in mood, energy, activity levels and the ability to carry out day-to-day tasks. "Previous studies of RNA expression in the postmortem brains of patients with MDD and bipolar disorder have shown alterations in the expression of lysosome‐related genes, including MCOLN1 and ATG16L2." (PMID 39264289, 2024).
cognitive decline (1 paper, 2014). "Since our data show no overt neuronal loss in the Mcoln1−/− brain, we next examined the consequence of loss of TRPML1 on neuronal function, which might explain the severe motor and cognitive decline in MLIV." (PMID 25200117, 2014).
colon adenocarcinoma (1 paper, 2023). "The findings unveiled a novel three TRP channels-related gene signature (MCOLN1, TRPM5, and TRPV4) in colon adenocarcinoma (COAD)." (PMID 38188686, 2023).
colorectal adenocarcinoma (1 paper, 2023). The most common type of colorectal carcinoma. "Furthermore, we identified two genes, TUBA1A and MCOLN1, which are associated with TSA and colorectal adenocarcinoma." (PMID 37072452, 2023).
Hypertension (1 paper, 2021). The presence of chronic increased pressure in the systemic arterial system. "Consequently, mice deficient in TRPML1 (Mcoln1–/–) resulted in excessive vasoconstriction and hypertension." (PMID 33716794, 2021).
insulinomas (1 paper, 2023). "ROC curves with areas under the curve (AUC) are shown for investigating the diagnostic effectiveness of the nomogram model between insulinoma and NFPNET by using the identified three target genes (ATP4A, MCOLN1, and ATP6V0E1)." (PMID 37772258, 2023). "In summary, these outcomes suggest that ATP4A, MCOLN1, and ATP6V0E1 are crucially ion channel-related genes in insulinoma, and the diagnostic model based on these genes was highly efficient." (PMID 37772258, 2023). "Since ATP4A, MCOLN1, and ATP6V0E1 might be pivotal in the ion channels for insulinoma and participate in regulating the secretion of various hormones, we selected these three target genes separately for further single-gene GSEA and GSVA analyses." (PMID 37772258, 2023). "In summary, MCOLN1, ATP6V0E1, and ATP4A might enhance the insulin secretion of insulinomas by participating in regulating the function and TGF-beta signaling pathway." (PMID 37772258, 2023). "Exploring potential therapeutic drugs for targeting ATP4A, MCOLN1, and ATP6V0E1 might offer a definite treatment approach to symptom improvement of insulinoma." (PMID 37772258, 2023).
leukemia (1 paper, 2022). A malignant (clonal) hematologic disorder, involving hematopoietic stem cells and characterized by the presence of primitive or atypical myeloid or lymphoid cells in the bone marrow and the blood. "The genes in the leukemia cell line term were AFDN (alias MLLT4, chromosome 1, WHWT), KLF3 (chromosome 3, LR), RPS6, (chromosome 5, LR), and FCER2, MCOLN1, and PRAM1 on chromosome 20 (GSD)." (PMID 36482174, 2022).
Lewy body disease (1 paper, 2023). "Of note, MCOLN1 gene variants have been linked to Lewy body disease." (PMID 37998376, 2023).
myopia (1 paper, 2020). "It is possible that the rapid initial decrease to a stable value may result from retinal thinning as the eye enlarges due to myopia during postnatal development, an occasionally observed feature of MCOLN1-associated disease in humans." (PMID 32290105, 2020).
Sepsis (1 paper, 2025). Sepsis is defined as life-threatening organ dysfunction caused by a dysregulated host response to infection. "Moreover, MCOLN1-mediated lysosomal exocytosis exacerbates lipopolysaccharide (LPS)-induced secretion of SQSTM1, an autophagy receptor, which has been implicated in immune dysfunction and organ injury in sepsis patients." (PMID 40761792, 2025). "We identified significant colocalization evidence for MCOLN1 (mucolipin 1) and IGF1R in relation to sepsis in critical care, with posterior probability of colocalization (PPH4) values of 0.705 and 0.732, respectively." (PMID 40761792, 2025). "Moreover, IGF1R and MCOLN1, supported by MReQTL, SMR, and colocalization evidence, exhibited strong binding affinities for chlorogenic acid, which is widely recognized for its anti-inflammatory effects in sepsis." (PMID 40761792, 2025).
cancer (54 papers, 2018 to 2025). A tumor composed of atypical neoplastic, often pleomorphic cells that invade other tissues. "MCOLN1/TRPML1, a key player in autophagy, is implicated in various cancers by promoting carcinogenic autophagy." (PMID 39744692, 2025). "Using datasets available at the cancer genome atlas (TCGA), we found that the gene encoding the endolysosomal cation channel, TRPML1 (MCOLN1), was upregulated in oncogenic HRAS-expressing tumors due to the combined actions of MiTF and TFEB." (PMID 31526156, 2019). "Mucolipin transient receptor potential channel 1 (TRPML1), encoded by MCOLN1, demonstrated significantly increased expression in OVCAR8 when compared to both normal cells (HK2) and cisplatin-sensitive cancer cells (TOV21G)." (PMID 38247807, 2024). "The expression of Cd52, Snap29, Mcoln1 and Nek6 genes, known to promote tumorigenesis in different cancer types, was up-regulated in peritoneal TCL1-Tg CLL cells." (PMID 38469292, 2024). "Selective inhibition of TRPML1 or Knockdown of MCOLN1 reduces cancer proliferation by disrupting oncogenic HRAS clustering localized in the plasma membrane." (PMID 38247807, 2024). "Recently, the endolysosomal cation channel TRPML1 (also known as MCOLN1) has gained focus in cancer research because it represents an interesting novel target." (PMID 35274126, 2022). "We recently showed that human cancers with activating mutations in HRAS elevate the expression of MCOLN1, which encodes an endolysosomal cation channel called TRPML1." (PMID 31526156, 2019). "Moreover, MCOLN1/TRPML1 finely controls oncogenic autophagy in cancer by mediating zinc influx into the cytosol." (PMID 38188686, 2023). "Thus, MCOLN1 has great potential in inhibiting cancer progression and represents a promising drug target for cancer treatment." (PMID 38188686, 2023). "Consistently, a high expression level of TFEB-mediated Wnt target genes, but not MCOLN1, was associated with poor prognosis in cancer patients." (PMID 33753903, 2021). "Similarly, MCOLN1 is upregulated in HRAS-expressing cancer cells and plays a role in HRAS-positive-tumor proliferation." (PMID 31867325, 2019). "Despite the emerging role of TRPML1 in a range of cellular functions, including cationic lysosomal homeostasis, cell repair and, more recently, aging and cancer, the time course of Mcoln1/TRPML1 expression during the development of living tissue has not been tracked." (PMID 32586947, 2020). "We evaluated the distribution of the TRP family in C1–C6 pan-cancer immune subtypes and observed that TRPC4, TRPC6, TRPM4, TRPV2, TRPV4, MCOLN1, and PKD2L1 had the potential to predict the immune subtype." (PMID 36830651, 2023). "Accompanying the increase in MCOLN1 expression, TRPML1-mediated endolysosomal Ca2+ release was dramatically higher in HRAS-driven cancer cells compared to controls." (PMID 31526156, 2019). "Interestingly, MCOLN1 knockdown or TRPML1 inhibition did not affect ERK phosphorylation and cell proliferation in cancer cells expressing wild-type HRAS, or in cells in which oncogenic HRAS was stably knocked down." (PMID 31526156, 2019).
tumor (31 papers, 2014 to 2025). "MCOLN1 is upregulated in triple-negative breast cancer cell lines, and it mediates tumor development via the mTORC1 pathway and lysosomal ATP release." (PMID 31867325, 2019). "According to these data, we can infer that mucolipin-1 (MCOLN1) might act as a mediator of tumor angiogenesis." (PMID 31867325, 2019). "The results show that TRPV4, MCOLN1,and TRPM5 are expressed differently between normal and tumor tissues." (PMID 38188686, 2023). "The three genes (MCOLN1, MCOLN2, and MCOLN3) coding for the mucolipin subfamily of TRP channels were also down-regulated in tumor tissues." (PMID 24466154, 2014).
neurodegenerative disease (21 papers, 2016 to 2025). A disorder of the central nervous system characterized by gradual and progressive loss of neural tissue and neurologic function. "Future proteomic studies using Mcoln1−/− brain tissues are warranted to yield better insight into the mechanistic processes that underlie zinc dyshomeostasis in MLIV and other neurodegenerative diseases." (PMID 30914059, 2019).
infection (7 papers, 2015 to 2023). The state of being infected such as from the introduction of a foreign agent such as serum, vaccine, antigenic substance or organism. "Both infectious HIV and AT-2-inactivated HIV increased the transcription of ATG9B, UVRAG, and MCOLN1 suggesting activation of TFEB by HIV does not require productive infection." (PMID 26115100, 2015).
neurological disorders (3 papers, 2020 to 2022). "Moreover, loss of function mutations in MCOLN1 are responsible for the onset of neurological disorders." (PMID 32411610, 2020).
brain disease (2 papers, 2023 to 2024). "This study provides a protein fingerprint of MLIV brain disease in Mcoln1−/− mice, confirming previously known pathological hallmarks and adding new depth to the understanding of the molecular changes and pathways underlying the disease." (PMID 37609073, 2023).